P2RX6 (purinergic receptor P2X 6)
Description:
May act as a modulatory subunit rather than a functional channel. Unlike other P2XRs members, P2RX6 does not seem to form functional homotrimers. P2RX6 requires the presence of P2RX4 or P2RX2 to shuttle it to the plasma membrane where it may form functional heterotrimeric receptors at the plasma membrane. P2RX6 can be translocated to the nucleus and functions as a nuclear regulator of post-transcriptional modifications in neurons (By similarity).
Synonyms: P2X6; P2RXL1; P2XM; MGC129625
Tractability: Small molecule: it belongs to a druggable protein family. Antibody: its Gene Ontology location is reachable by antibodies, with high confidence; UniProt places it where antibodies can reach, with medium confidence; UniProt predicts a signal peptide or a membrane-spanning region.
Target class: Ligand-gated ion channel; P2X receptor; Ion channel
Safety:
Unwanted effects reported when the protein is acted on. In parentheses: how it was acted on, where the effect was seen, and who reports it.
decreased convulsions (inhibition, acute dosing; nervous system, renal, immune; source: Lynch et al. (2017))
decreased inflammation (inhibition, acute dosing; nervous system, renal, immune; source: Lynch et al. (2017))
decreased pain (inhibition, acute dosing; nervous system, renal, immune; source: Lynch et al. (2017))
hemolysis (activation, acute dosing; nervous system, renal, immune; source: Lynch et al. (2017))
increased pain (activation, acute dosing; nervous system, renal, immune; source: Lynch et al. (2017))
increased urinary sodium excretion (activation, acute dosing; nervous system, renal, immune; source: Lynch et al. (2017))
increased urine excretion (activation, acute dosing; nervous system, renal, immune; source: Lynch et al. (2017))
neurodegeneration (activation, chronic dosing; nervous system, renal, immune; source: Lynch et al. (2017))
Gene: Protein-coding gene on chromosome 22 (21,009,808 to 21,028,013, forward strand). Ensembl gene ENSG00000099957.
Subcellular location: Cell membrane; Endoplasmic reticulum; Nucleus; Nucleus inner membrane
Subcellular location (Human Protein Atlas): Cytosol; Nucleoli
Pathways (Reactome):
Hemostasis: Elevation of cytosolic Ca2+ levels; Platelet homeostasis
Gene Ontology:
Molecular function: ATP binding; channel activity; extracellularly ATP-gated monoatomic cation channel activity; purinergic nucleotide receptor activity; transmembrane signaling receptor activity; monoatomic ion channel activity; protein-containing complex binding
Biological process: calcium ion transmembrane transport; muscle contraction; signal transduction; excitatory postsynaptic potential; monoatomic cation transmembrane transport; monoatomic ion transport; purinergic nucleotide receptor signaling pathway; response to ATP
Cellular component: cell junction; cytoplasm; receptor complex; endoplasmic reticulum; nuclear inner membrane; nucleus; plasma membrane; dendritic spine; endoplasmic reticulum membrane; glutamatergic synapse; membrane; neuronal cell body; parallel fiber to Purkinje cell synapse; postsynaptic specialization membrane
Genetic constraint (gnomAD): Loss-of-function variants: 63 observed, 50.74 expected, observed/expected ratio (o/e) 1.24, 90% interval 1.01 to 1.53. The upper end of that interval is the gene's LOEUF score, 1.53, which puts it in group 6 of 6, group 1 being the genes least tolerant of losing a copy. Missense variants: 541 observed, 510.27 expected, observed/expected ratio (o/e) 1.06, 90% interval 0.99 to 1.14. Synonymous variants: 211 observed, 202.56 expected, observed/expected ratio (o/e) 1.04, 90% interval 0.93 to 1.17.
Homologues: Orthologues: chimpanzee P2RX6 (99% identical), rabbit P2RX6 (78% identical), pig P2RX6 (76% identical), guinea pig P2RX6 (73% identical), mouse P2rx6 (72% identical), macaque P2RX6 (71% identical), rat P2rx6 (70% identical), tropical clawed frog p2rx6 (47% identical). Paralogues in human: P2RX5 (40% identical), P2RX4 (38% identical), P2RX1 (36% identical), P2RX2 (35% identical), P2RX3 (34% identical), P2RX7 (32% identical).
Diseases named in the same sentence as P2RX6 in open-access papers:
P2RX6 is named in the same sentence as 21 diseases in open-access papers, as found by Europe PMC text mining. Sharing a sentence is not in itself a finding about the gene and the disease. The quoted sentences say what the papers report.
renal carcinoma (8 papers, 2019 to 2024). A carcinoma arising from the epithelium of the renal parenchyma or the renal pelvis. "P2RX6 encodes a P2X receptor that increases renal cancer cell migration and invasion." (PMID 38177502, 2024). "METTL14 inhibits the migration and invasion of renal cancer cells by downregulating purinergic receptor P2X 6 (P2RX6) protein translation and ATP-P2RX6-Ca2+-p-ERK1/2-MMP9 signalling in renal cell carcinomas." (PMID 35518355, 2022). "Increased m6A by METTL14 suppresses renal cancer cell migration and invasion through down-regulation of P2RX6 protein translation and ATP-P2RX6-Ca2+-p-ERK1/2-MMP9 signaling." (PMID 33922187, 2021). "In renal carcinoma, METTL14 was down-regulated and abrogated P2RX6 expression via m6A modification to suppress renal cancer cell migration and invasion." (PMID 34503454, 2021). "The m6A-suppressed P2RX6 activation promotes renal cancer cells migration and invasion through ATP-induced Ca2+ influx modulating ERK1/2 phosphorylation and MMP9 signalling pathway." (PMID 31159832, 2019). "A recent study reported that METTL14 could mediate P2RX6 mRNA and protein level, promoting renal cancer cells migration and invasion via ATP-induced Ca2+ influx modulating ERK1/2 phosphorylation and MMP9 signal pathway in vitro and in vivo assays." (PMID 32038982, 2020). "Moreover, the m6A-suppressed P2RX6 activation could promote renal cancer cells migration and invasion through ATP-induced Ca2 + influx modulating ERK1/2 phosphorylation and MMP9 signaling pathway." (PMID 33430867, 2021).
renal cell carcinoma (3 papers, 2020 to 2022). "Mechanistically, METTL14-guided m6A modification suppresses the purinergic receptor P2X 6 (P2RX6) protein translation, which is important for renal cell carcinoma migration and invasion." (PMID 32709063, 2020). "A similar METTL14 expression pattern was found in renal cell carcinoma, and METTL14 further suppressed P2RX6 activation regulated metastasis of renal cell carcinoma via ATP‐induced Ca2+ influx modulating ERK1/2 phosphorylation and MMP9 signalling." (PMID 32808488, 2020).
ischemia (1 paper, 2025). A hypoperfusion of the BLOOD through an organ or tissue caused by a PATHOLOGIC CONSTRICTION or obstruction of its BLOOD VESSELS, or an absence of BLOOD CIRCULATION. "Namely, the peptide reduced the expression of many genes (e.g., P2rx6, Gabra3, Grik4, Oprl1, Glra2, Crhr1, Hrh1, Chrm5, Grik1) related to the neurosignaling system and whose expression was not significantly changed by ischemia itself." (PMID 40650034, 2025).
neuropathies (1 paper, 2024). "The NGS analysis identified no additional variants within candidate genes associated with neuropathies or myopathy but revealed a novel homozygous deletion of the P2RX6 gene disrupting protein function." (PMID 38392191, 2024).
cancer (5 papers, 2019 to 2024). A tumor composed of atypical neoplastic, often pleomorphic cells that invade other tissues. "Several top-ranking IP genes were found in multiple cancer types, including ACCN2, GRIN2D, and TRPV3 that associated with poor prognosis in six cancer types, and P2RX6 in seven cancer types." (PMID 38177502, 2024). "METTL14 downregulation in cancer cells decreases the m6A levels in P2RX6 mRNA, thereby increasing its expression which leads to ERK1/2 MAPK pathway activation promoting RCC cell migration and invasion." (PMID 33814008, 2021). "In this study it is shown that, increased m6A modification is negatively correlated with cancer cell migration and invasion through alternative splicing and downregulation of P2RX6, a G-protein coupled Ca2+ ion channel and a preferred receptor for ATP binding." (PMID 33814008, 2021). "Among the remaining 8 DEGs (ADRA2A, P2RX6, XCL2, XCL1, CCL7, TRIM54, TNFRSF18 and SPOCK1), the expression of ADRA2A, the top one, in KIRC based on individual cancer is lower than the normal tissues, but patients with lower expressed ADRA2A have a better overall survival (OS)." (PMID 31159832, 2019).
tumor (4 papers, 1999 to 2022). "On the other hand, P2RX6 had the dramatically differential expression between normal and tumor tissues in our clinical samples." (PMID 31159832, 2019). "A RBM15B has lower expression in tumor tissues and B lower expression could result in a worse OS, and C has a positive correlation with P2RX6 expression in TCGA database." (PMID 31159832, 2019). "For example, BCL9L, P2RX6, RER1, EFNA2, CASK, CERCAM, and PTPRN were demonstrated to promote EMT, metastasis, and invasion of tumor cells." (PMID 35586092, 2022). "Meanwhile, FTO has higher expression in tumor tissues and a negative correlation with P2RX6 expression, but survival analysis has no significantly difference between two groups." (PMID 31159832, 2019). "However, RBM15B has lower expression in tumor tissues and lower expression could result in worse OS, also RBM15B has a positive correlation with P2RX6 expression in TCGA database." (PMID 31159832, 2019).
myopathy (1 paper, 2024). A disease of the muscle in which the muscle fibers do not function properly. "Further investigations, including muscular biopsy, are essential to confirm the association of the P2RX6 gene with myopathy, providing valuable insights into the structural and functional aspects of muscle tissue." (PMID 38392191, 2024). "In our research, we discuss the loss of function of P2RX6 to the dysregulation of signaling pathways, suggesting correlations with additional proteins also having potential roles in myopathy, including disturbances in mitochondrial oxidative processes." (PMID 38392191, 2024). "Notably, we are introducing, for the first time, a close association of the P2RX6 gene with myopathy." (PMID 38392191, 2024). "The primary objective of this research was to assess a potential correlation between the diagnosed myopathy in the patient and the homozygous (biallelic) deletion in the P2RX6 gene, as revealed by WES analysis." (PMID 38392191, 2024). "Whole exome sequencing (WES) did not detect potentially causative variants in known myopathy-associated genes but revealed a novel homozygous deletion of the P2RX6 gene likely disrupting protein function." (PMID 38392191, 2024).
neuromuscular disease (1 paper, 2024). "This approach allowed for a comprehensive exploration of potential interactions, enhancing our understanding of the roles played by the P2RX6 protein in the mechanism involving molecular chaperones in neuromuscular diseases." (PMID 38392191, 2024).
P2RX6 also shares sentences with these, for which no sentence is quoted: benign tumors (1 paper); breast carcinoma (1); cardiovascular diseases (1); cystic fibrosis (1); embryonal carcinoma (1); gastric cancer (1); ischemic stroke (1); morbid obesity (1); neuroblastoma (1); neurodegenerative disease (1); Parkinson disease (1); sarcoma (1); soft-tissue tumours (1).